TMEM196 (transmembrane protein 196)
Description:
Acts as a tumor suppressor in lung cancer. Inhibits tumor cell growth by inhibiting cell proliferation and migration and promoting cell apoptosis. Inhibits metastasis of lung cancer by suppressing beta-catenin expression in the Wnt/beta-catenin signaling pathway (By similarity).
Synonyms: MGC42090
Tractability: Antibody: UniProt predicts a signal peptide or a membrane-spanning region.
Gene: Protein-coding gene on chromosome 7 (19,719,315 to 19,773,617, reverse strand). Ensembl gene ENSG00000173452.
Subcellular location: Cytoplasm; Membrane
Subcellular location (Human Protein Atlas): Golgi apparatus; Nucleoplasm
Gene Ontology:
Biological process: negative regulation of cell growth; negative regulation of cell migration; negative regulation of cell population proliferation; positive regulation of apoptotic process; negative regulation of canonical Wnt signaling pathway
Cellular component: cytoplasm; membrane
Genetic constraint (gnomAD): Loss-of-function variants: 17 observed, 18.78 expected, observed/expected ratio (o/e) 0.91, 90% interval 0.62 to 1.36. The upper end of that interval is the gene's LOEUF score, 1.36, which puts it in group 5 of 6, group 1 being the genes least tolerant of losing a copy. Missense variants: 264 observed, 230.92 expected, observed/expected ratio (o/e) 1.14, 90% interval 1.03 to 1.27. Synonymous variants: 112 observed, 91.52 expected, observed/expected ratio (o/e) 1.22, 90% interval 1.05 to 1.43.
Homologues: Orthologues: chimpanzee TMEM196 (100% identical), dog TMEM196 (100% identical), guinea pig TMEM196 (100% identical), pig TMEM196 (99% identical), rabbit TMEM196 (99% identical), macaque TMEM196 (99% identical).
Diseases named in the same sentence as TMEM196 in open-access papers:
TMEM196 is named in the same sentence as 9 diseases in open-access papers, as found by Europe PMC text mining. Sharing a sentence is not in itself a finding about the gene and the disease. The quoted sentences say what the papers report.
lung carcinoma (4 papers, 2015 to 2026). "Low TMEM196 expression was associated with worse prognosis than high TMEM196 expression, and TMEM196 served as an independent prognostic biomarker for lung cancer." (PMID 41596760, 2026). "TMEM196 downregulation or inactivation is associated with promoter methylation in both rat and human primary lung cancer tissues and cell lines." (PMID 41596760, 2026). "Next, we analysed the association of TMEM196 methylation status and clinicopathological characteristics in 62 lung cancer patients with all parameters available." (PMID 26056045, 2015). "The results showed that low TMEM196 expression was significantly associated with shorter survival for TNM stage I–II lung cancer patients." (PMID 26056045, 2015). "Kaplan–Meier survival curves showed that TMEM196 downregulation was significantly associated with shortened survival in lung cancer patients." (PMID 26056045, 2015). "TMEM196 methylation correlated with loss of protein expression in chemical-induced rat lung pathologic lesions and human lung cancer tissues and cell lines." (PMID 26056045, 2015). "Through genome-wide methylation screening, we identified a novel preferentially methylated gene, transmembrane protein 196 (TMEM196), in human lung cancer, suggesting that it may be associated with lung tumourigenesis." (PMID 26056045, 2015). "Moreover, TMEM196 hypermethylation was detected in 61.2% of primary lung tumours and found to be associated with poor differentiation and pathological stage of lung cancer." (PMID 26056045, 2015). "However, TMEM196 methylation was associated with poor differentiation (P = 0.039) and pathological stage (P = 0.017) of lung cancer." (PMID 26056045, 2015). "TMEM196 hypermethylation in lung cancer tissues was later verified in the TCGA database compared with adjacent normal tissues." (PMID 41596760, 2026). "Consistent downregulation of TMEM196 was confirmed in lung cancer tissues in comparison with adjacent normal tissues in both the TCGA database and independent lung cancer patient cohorts analyzed via IHC." (PMID 41596760, 2026). "For example, TMEM196 silencing in lung cancer cells and mice resulted in the upregulation of MMP2 and MMP7." (PMID 37367036, 2023). "TMEM196 overexpression suppressed the expression of MMP2, and of MMP7 in lung cancer cells, whereas TMEM196 knockdown had the opposite effect." (PMID 37367036, 2023). "In the present study, we studied the promoter methylation and expression status of TMEM196 in a chemical-induced rat lung cancer model, primary human tumour tissues and multiple lung cancer cell lines." (PMID 26056045, 2015). "Next, we evaluated TMEM196 methylation status in 85 cases of human primary lung cancer and 20 cases of normal lung tissue." (PMID 26056045, 2015). "This suggests that TMEM196 expression was an independent predictor of poorer survival of patients with lung cancer." (PMID 26056045, 2015). "The results showed that all 10 lung cancer cell lines in our study show TMEM196 hypermethylation, while the normal human bronchial epithelial cell line HBE exhibited unmethylation status." (PMID 26056045, 2015). "In summary, our study identified TMEM196 as a functional tumour suppressor with frequent epigenetic inactivation in lung cancer." (PMID 26056045, 2015). "To further confirm the tumour suppressor role of TMEM196 in lung cancer, we used siRNA vector transfection to knockdown TMEM196 expression in the TMEM196-expressing cell line HBE." (PMID 26056045, 2015). "TMEM196 expression level was inversely correlated with the methylation status in all lung cancer cell lines, except H358 cells, and HBE cells." (PMID 26056045, 2015). "Functional studies showed that ectopic re-expression of TMEM196 in lung cancer cells inhibited cell proliferation, clonogenicity, cell motility and tumour formation." (PMID 26056045, 2015). "We then evaluated the methylation status of TMEM196 in several human lung cancer cell lines using MSP." (PMID 26056045, 2015).
lung carcinoma (continued). "Kaplan–Meier survival curves showed that lung cancer patients with low TMEM196 expression had significantly shorter survival than those with high TMEM196 expression (P < 0.001, log-rank test)." (PMID 26056045, 2015). "We found that TMEM196 was expressed at low levels in lung cancer tumour tissues and expressed at high levels in adjacent tissue sample." (PMID 26056045, 2015). "Our results revealed for the first time that TMEM196 acts as a novel functional tumour suppressor inactivated by DNA methylation and is an independent prognostic factor of lung cancer." (PMID 26056045, 2015). "In the future, the sputum and plasma data should be validated in a large prospective screening study for lung cancer, and TMEM196 methylation should be combined with other methylation markers to enhance the sensitivity and/or specificity." (PMID 26056045, 2015). "TMEM196 expression was downregulated in lung cancer tissues compared with their adjacent normal tissues." (PMID 26056045, 2015). "We further investigated the biological functions, molecular basis and clinical significance of TMEM196 in lung cancer." (PMID 26056045, 2015). "TMEM196 expression, predominantly localized in the cytoplasm, was significantly downregulated at both the mRNA and protein levels in lung cancer cell lines and human lung tumor tissues (including LUAC and LUSC) compared with normal HBE cells and adjacent normal tissues." (PMID 41596760, 2026). "TMEM196 inhibited tumor metastasis and the progression of lung cancer in vitro and in vivo." (PMID 37367036, 2023). "The methylation-mediated silencing of TMEM196 may serve as a potential epigenetic biomarker for early diagnosis and a therapeutic target for patients with lung cancer." (PMID 26056045, 2015). "We further evaluate the clinical significance and prognostic value of TMEM196 in lung cancer." (PMID 26056045, 2015). "Using genome-wide methylation screening, we identified TMEM196 hypermethylation in lung cancer." (PMID 26056045, 2015). "We recently found that TMEM196 was hypermethylated in lung cancer." (PMID 26056045, 2015). "We used the wound healing assay to detect the effect of TMEM196 on lung cancer cell motility." (PMID 26056045, 2015). "Furthermore, we showed that the TMEM196 gene is frequently methylated in the chemical-induced rat lung cancer model, and the methylation frequency correlated with the lung pathologic lesions and loss of expression of the protein." (PMID 26056045, 2015). "From our findings, we propose the hypothesis that TMEM196 expression may function as a potential tumour suppressor in lung cancer." (PMID 26056045, 2015). "We found that ectopic expression of TMEM196 in lung cancer cell lines SPC-A-1 and H1975 could inhibit cell growth, colony formation and tumour formation in nude mice." (PMID 26056045, 2015). "To clarify whether DNA hypermethylation regulated the expression of TMEM196 gene, we examined TMEM196 mRNA expression in 10 human lung cancer cell lines and the normal HBE cell line by reverse transcription-polymerase chain reaction (RT-PCR) and quantitative RT-PCR." (PMID 26056045, 2015). "However, few studies have investigated the regulation of TMEM196, and the role and function of TMEM196 in lung cancer remain unknown." (PMID 26056045, 2015). "Approximately 50 TMEMs have been found to be deregulated and have been studied in lung cancer; some predominantly act as tumor suppressors (e.g., TMEM100 and TMEM196), while others function as oncogenes (e.g., TMEM14A and TMEM158)." (PMID 41596760, 2026). "TMEM196 hypermethylation was observed in chemically induced rat lung lesions, human lung cancer tissues, and cell lines but not in normal lung tissues or HBE cells." (PMID 41596760, 2026). "In this study, we found that TMEM196 was hypermethylated in human primary lung cancer tissues and cell lines but not in corresponding normal tissues." (PMID 26056045, 2015).
lung carcinoma (continued). "We next evaluated TMEM196 mRNA expression in 10 primary lung cancers and their corresponding adjacent non-tumour tissues by RT-PCR." (PMID 26056045, 2015).
colorectal cancer (1 paper, 2015). A primary or metastatic malignant neoplasm that affects the colon or rectum. "Previous studies found that HPP1, VEZT and IFITM3, which contain a similar transmembrane domain to that of TMEM196, were hypermethylated associated with downregulation in colorectal cancer, gastric cancer and melanoma, respectively." (PMID 26056045, 2015).
dysplasia (1 paper, 2015). A usually neoplastic transformation of the cell, associated with altered architectural tissue patterns. "There was a statistically significant negative correlation between TMEM196 promoter methylation and its protein expression during chemically induced rat lung carcinogenesis, especially in the stages of squamous metaplasia, dysplasia, CIS and infiltrating carcinoma (P < 0.01)." (PMID 26056045, 2015).
tumor (3 papers, 2015 to 2026). "Gain and loss-of-function studies consistently demonstrate that TMEM196 suppresses tumor metastasis and progression both in vitro and in vivo." (PMID 41596760, 2026). "In the univariate Cox regression analysis, TMEM196 expression in tumour tissues was associated with a decreased risk of cancer-related death (hazard ratio (HR) = 0.456; 95% confidence interval (CI), 0.253–0.822; P = 0.009)." (PMID 26056045, 2015). "Molecular studies revealed that the tumour suppressive role of TMEM196 was closely associated with its pro-apoptotic effect." (PMID 26056045, 2015). "After adjustment for potential confounding factors, TMEM196 expression in tumour tissues was found to predict better survival (HR = 0.357; 95% CI, 0.204–0.624; P = 0.0003) in the multivariate model." (PMID 26056045, 2015). "We found that TMEM196 expression in tumour tissues was found to predict better survival in the multivariate model." (PMID 26056045, 2015). "To clarify the molecular mechanism of the inhibition effect of tumour cell growth by TMEM196, we examined the cell cycle and apoptosis by flow cytometry." (PMID 26056045, 2015). "BGS results were in good agreement with the MSP findings, with TMEM196 being densely methylated at the promoter in most of the cell lines, partially methylated in tumour tissues and unmethylated in normal tissues." (PMID 26056045, 2015). "We found that the average size and weight of tumours induced by TMEM196-expressing cells significantly decreased compared with the controls (P < 0.01)." (PMID 26056045, 2015). "The tumour suppressing effects of TMEM196 was demonstrated in H358 cells with normal TMEM196 expression levels." (PMID 26056045, 2015). "To further determine the tumour suppressive ability of TMEM196 in vivo, we evaluated tumour formation in nude mice." (PMID 26056045, 2015). "CpG methylation of TMEM196 was detectable in various precancerous and tumour cells after laser capture microdissection." (PMID 26056045, 2015). "Confluent monolayers of vector- and TMEM196-transfected SPC-A-1 and H1975 tumour cells were scratched 48 h after transfection." (PMID 26056045, 2015).
TMEM196 also shares sentences with these, for which no sentence is quoted: cancer (2 papers); gastric cancer (1); lung (1); melanoma (1); Obesity (1).